FGF23 (fibroblast growth factor 23)
Diseases named in the same sentence as FGF23 in open-access papers (continued):
Sharing a sentence is not in itself a finding about the gene and the disease.
heart failure (continued). "Heart failure stands as the second most prevalent cause of secondary FGF23 overload." (PMID 38846254, 2024). "Higher cFGF23 levels are associated with increased risks of mortality and heart failure, which may be driven by direct, toxic effects of FGF23 on the heart." (PMID 38402503, 2024). "Our findings imply that physicians should be aware of the risk of heart failure in patients with EP, and that serum FGF23 may represent a marker of the risk of heart failure in such patients." (PMID 37593148, 2023). "In addition, high FGF23 concentration was shown to be associated with new-onset heart failure in a cohort study of members of the general population." (PMID 36909314, 2023). "This initiated a search for FGF-23 and heart failure associations." (PMID 35743683, 2022). "Furthermore, elevated FGF23 has been linked to volume overload, a common manifestation of heart failure." (PMID 34765890, 2021). "In conclusion, this meta-analysis of RCTs demonstrates that vitamin D administration of >2000 IU/d vitamin D or activated vitamin D significantly increased concentrations of the cardiovascular risk marker FGF23, especially in patients with end-stage kidney/heart failure." (PMID 32855522, 2021). "Heart failure (HF) is the second most common cause of secondary FGF23 excess." (PMID 34330955, 2021). "In hemodialysis patient with secondary hyperparathyroidism, higher baseline serum FGF23 levels are associated with an increased risk for the primary outcome (death, first myocardial infarction, hospitalization for unstable angina, heart failure or peripheral vascular event)." (PMID 33416083, 2021). "Studies looking at heart failure admissions have also shown an association with baseline FGF23." (PMID 34600515, 2021). "In addition, FGF-23 is independently associated with all-cause death and incident heart failure in community-living older individuals." (PMID 34297744, 2021). "Elevated FGF23 has been associated with left ventricular dysfunction and AF in patients without cardiovascular co-morbidities, including incident AF after correction for eGFR, albuminuria, and heart failure events, and confirmed in patients with CKD." (PMID 33534825, 2021). "Our previous study showed that FGF23 overexpression could worsen heart failure, while high levels of FGF23 were significantly associated with the severity of heart failure." (PMID 33460402, 2021). "Here, a more than 30% reduction of FGF23 in 20 weeks among participants allocated to cinacalcet, was associated with a reduced risk on the composite outcome of cardiovascular mortality, sudden cardiac death and heart failure." (PMID 32130720, 2020). "Fibroblast growth factor-23 (FGF-23), a hormone involved in phosphorus metabolism that increases progressively as kidney function declines, was significantly associated with mortality, atherosclerotic events, heart failure (HF), and ESKD in CKD patients." (PMID 32823966, 2020). "In patients with combined type 2 diabetes and CAD, FGF-23 independently predicts adverse cardiovascular outcome and, additionally, elevated FGF-23 concentrations following acute coronary syndrome are associated with an increased risk of CV death and hospitalization due to heart failure." (PMID 32998751, 2020). "Finally, uni- and multivariate Cox regression analysis adjusted for age and sex revealed an association between FGF23 and event-free survival independently of established predictors in heart failure, such as NT-proBNP, LV-EF, and eGFR." (PMID 29849175, 2018). "High FGF23 levels and klotho deficiency are postulated as key risk factors for the development of uremic cardiomyopathy and increase of FGF23 is further associated with poor outcome in patients with heart failure, cardiogenic shock, or arrhythmia at normal kidney function." (PMID 29977226, 2018). "If alkali therapy does indeed increase FGF23, this could contribute to the risk of heart failure in patients with CKD." (PMID 27495287, 2016).
heart failure (continued). "Serum FGF23 levels are positively correlated with the risk of heart failure." (PMID 26483756, 2015). "However, few studies have focused on this condition.This study is aimed to assess the prevalence and factors associated with heart failure in EP patient, and to the measure the serum concentrations of fibroblast growth factor 23 (FGF23), a potential predictor of chronic heart failure." (PMID 37593148, 2023). "Additionally, we evaluated whether baseline values of klotho and FGF-23 were associated with 1-month changes in peak oxygen consumption (peak VO2) in stable outpatients with heart failure with reduced ejection fraction (HFrEF)." (PMID 37745119, 2023). "In addition to its main action, the role of FGF23 in cardiac dysfunction is also attracting considerable attention because an increase in plasma FGF23 levels is associated with the risk of heart failure and circulating FGF23 is considered a possible biomarker for heart failure." (PMID 32315372, 2020). "We assessed whether RDW is associated with FGF23 cleaving in CKD patients with heart failure." (PMID 26079688, 2015). "Several biomarkers—including IGFBP-1, IGFBP-2, IGFBP-3, FGF-23, MMP-2, MMP-7, TIMP-2, and RAGE/AGE—were significantly elevated in patients with cardiac involvement and independently associated with either heart failure decompensation or death/transplantation." (PMID 41226753, 2025). "While individual profibrotic markers such as FGF-23 or IGFBPs have been previously studied in heart failure, their combined assessment in ATTR-CA and the identification of specific cluster-based phenotypes have not, to our knowledge, been reported yet." (PMID 41226753, 2025). "In summary, FGF-23 is a pivotal marker and possible mediator in the interplay between kidney dysfunction and heart failure." (PMID 41157213, 2025). "Data from heart failure patients also show elevated FGF23 levels in serum and in bone marrow plasma." (PMID 41515999, 2025). "In agreement with our data, studies in heart failure patients found a correlation between increased levels of circulating FGF23 and LV fibrosis." (PMID 41152461, 2025). "Therefore, in the present study, we aimed to assess the prevalence of and factors associated with heart failure in patients with EP, and to measure their serum FGF23 concentrations, to determine whether this might represent a useful predictor of chronic heart failure events in patients with EP." (PMID 37593148, 2023). "The elevated levels of BNP and FGF-23 suggest a potential link between osteoporosis and the worsening of heart failure." (PMID 37874407, 2023). "The heart produced FGF23 in animal models of pathological conditions, including heart failure, LVH, and myocardial infarction." (PMID 38174329, 2023). "This substudy aimed to assess the changes in klotho and FGF-23 levels 1-month after dapagliflozin in patients with stable heart failure and reduced ejection fraction (HFrEF)." (PMID 37745119, 2023). "In these studies, serum FGF23 levels were also elevated, probably due to kidney dysfunction followed by heart failure." (PMID 38174329, 2023). "The scientific literature moreover suggests a relation between FGF-23 and heart failure/reduced left-ventricular ejection fraction." (PMID 37600039, 2023). "Oncostatin M is part of the interleukin-6 (IL-6) family and regulates remodeling and PTH effects in bone as well as cardiac FGF23 production in heart failure via glycoprotein gp130." (PMID 37225713, 2023). "Fibroblast growth factor-23 (FGF23) has been associated to left ventricular (LV) hypertrophy and heart failure (HF) severity." (PMID 37658340, 2023). "The up-regulation of serum FGF23 expression in elderly CHD patients complicated with heart failure after PCI can be used as a reliable indicator of prognosis." (PMID 35546659, 2022). "Then, some controversies about the differences of FGF-23 impact on prognosis between HFpEF and heart failure with reduced ejection fraction (HFrEF) arose." (PMID 35743683, 2022).
heart failure (continued). "Elevated circulating FGF23 levels are associated with accelerated disease progression, morbidity, and/or mortality in several clinical disorders, including CKD but also cardiac failure." (PMID 35884995, 2022). "Low-dose propranolol exerted cardio-preventative effects through FGF-23 downregulation and hemodynamic-parameter improvement in our model of hyper-acute catecholamine-induced heart failure." (PMID 35622651, 2022). "Fibroblast growth factor (FGF)-23 induces hypertrophy and calcium (Ca2+) dysregulation in cardiomyocytes, leading to cardiac arrhythmia and heart failure." (PMID 35008591, 2021). "Recent data have highlighted the relevant direct FGF-23 effects on the myocardium, and high plasma levels of FGF-23 have been associated with adverse cardiovascular outcomes in humans, such as heart failure and arrhythmias." (PMID 33767635, 2021). "Higher FGF23 levels were further observed in stable ischaemic cardiomyopathy and heart failure (HF) with reduced ejection fraction (HFrEF)." (PMID 34422725, 2021). "A substantially increased degree of FGF23 was detected in the serum of ADHF patients, but not in their myocardium, indicating an endocrine mechanism of FGF23 action in heart failure." (PMID 34095143, 2021). "FGF23 remained elevated in patients with AF after adjusting for renal function, and NT-proBNP remained elevated after adjusting for heart failure." (PMID 33534825, 2021). "A role of mineral metabolism in heart failure has been previously suggested in studies on FGF23, which is a bone-derived hormone that plays a well-established role in CKD patients." (PMID 34222283, 2021). "Considering the failing heart is a major source of circulating FGF23, we postulated an increase of plasma FGF23 in patients with heart failure would contribute to kidney injury." (PMID 33460402, 2021). "In this study, we found that not only cardiac FGF23 but also the expression levels of FGF23 in kidney and circulating were increased in MI mice with heart failure, in good agreement with previous reports." (PMID 33460402, 2021). "Individuals with higher FGF-23 levels also had a higher prevalence of prior heart failure, prior MI, and prior stroke/transient ischemic attack, and lower eGFR." (PMID 34297744, 2021). "Mechanistically, the adverse FGF23 effect is associated with macrophage-oncostatin M (OSM) signaling, which is a prominent mediator of heart failure." (PMID 34095143, 2021). "Whereas klotho did not predict CV events (death, atherosclerotic events, and decompensated heart failure) in patients CKD stages 2–4, FGF23, on the other hand, was significantly associated with future decompensated heart failure." (PMID 32106499, 2020). "Across quartiles of FGF-23, those in the highest quartile were more likely to have comorbid conditions such as diabetes, hypertension, coronary artery disease, and heart failure." (PMID 33306729, 2020). "New studies showed that FGF23 is increased during heart failure and correlates with cardiac complications and mortality." (PMID 32309615, 2019). "Elevation of circulating FGF23 levels are demonstrated in both animal heart failure model and in patients with acute decompensated heart failure or myocardial infarction and are associated with poor prognosis." (PMID 30200452, 2018). "Increased circulating FGF-23 has also been shown to predict incident and worsening heart failure, atrial fibrillation, cardiovascular events, and mortality." (PMID 29850246, 2018). "The basic levels of myocardial FGF23 mRNA and protein expression in mice were relatively low, but they were significantly up-regulated in heart failure induced by transverse aortic constriction (TAC) as evidenced by conventional PCR and immunochemistry." (PMID 27579618, 2016). "The macrophage/OSM axis is the major mechanism of cardiac FGF23 expression and release into the circulation in heart failure, indicating that FGF23 as a paracrine signal is a promising biomarker of OSM-dependent heart diseases." (PMID 27803896, 2016).
heart failure (continued). "Even in the general population, FGF23 levels are associated with death, cardiovascular disease (CVD), and heart failure (HF)." (PMID 26491212, 2015). "Since LVH is an independent risk factor, among others, for coronary heart disease (CHD), heart failure and stroke epidemiologic studies have investigated possible relationships between FGF23 and major CVD endpoints in the general population." (PMID 26193703, 2015). "Multiple studies have indicated that increased FGF23 levels are correlated with cardiovascular disorders (such as heart failure, atrial fibrillation, myocardial infarction and stroke) and an increased risk of both cardiovascular and non-cardiovascular mortality." (PMID 40863356, 2025). "Numerous recently published studies have illustrated the impact of acute kidney injury (AKI) on the susceptibility of cardiomyocytes to the induction of arrhythmias and a heart failure phenotype, which is correlated with elevated levels of FGF23 and reduced Klotho levels." (PMID 40863356, 2025). "In the high-risk group (low Klotho and high FGF23), the number needed to treat (NNT) with trandolapril to prevent one cardiovascular death or heart failure hospitalization event was nine, representing a 25% reduction compared to risk stratification based on FGF23 alone (NNT=12)." (PMID 38846254, 2024). "The elevation of FGF23 and the deficiency of Klotho collaboratively contribute to the activation of the RAS and its well-known adverse downstream effects, including cardiac remodeling and heart failure." (PMID 38846254, 2024). "Although not part of the primary analysis, FGF-23 was found to be an important biomarker for all-cause mortality and hospitalization for heart failure in crude models." (PMID 38524235, 2024). "Higher FGF23 levels are associated with increased cardiovascular risk, particularly heart failure-related events rather than events related to atherosclerotic diseases, while the relationship with stroke is less explored due to limited data." (PMID 38846254, 2024). "FGF23 levels predicted survival one year after hospitalization for acute heart failure in a critically ill patient group with the same accuracy as the Seattle Heart Failure (SHF) model." (PMID 38846254, 2024). "It included proteins like NT-proBNP (NPPB), growth differentiation factor 15 (GDF15), and fibroblast growth factor 23 (FGF23), markers that are known to be tightly related to heart failure and further systemic diseases, but also inflammatory proteins (CXCL8, CSF1)." (PMID 38999939, 2024). "Not surprisingly, reduced Klotho levels and elevated FGF23 concentrations have been associated with increased hospitalizations for heart failure and the incidence of cardiovascular death in a population of 3555 patients with stable ischemic heart disease." (PMID 37061530, 2023). "FGF-23 is also a strong predictor of outcome in heart failure patients." (PMID 37600039, 2023). "Beyond its secretion by osteocytes, FGF-23 was discovered to be expressed in cardiac myocytes and cardiac fibroblasts under pathologic conditions such as myocardial infarction, LV pressure overload and heart failure." (PMID 36790465, 2023). "Finally, high FGF23 has been shown to be an accurate predictor of chronic heart failure events and fatal outcomes in patients with heart failure and reduced ejection fraction (HFrEF)." (PMID 37593148, 2023). "However, combining the biomarkers identified here (BMP10, ANGPT2, FGF23) yielded larger improvements than NTproBNP in this cohort with known heart failure status." (PMID 37798357, 2023). "In addition, we found that patients with EP had significantly higher serum concentrations of FGF23, a marker of incident heart failure, than healthy individuals." (PMID 37593148, 2023). "However, the results of studies on the expression of FGF-23 protein in hearts with heart failure or LVH are relatively few and inconsistent." (PMID 34336893, 2021).
heart failure (continued). "This is in keeping with a previous finding that higher FGF-23 levels are associated with outcome in patients with heart failure with preserved ejection fraction, but not in those with HFrEF." (PMID 34222283, 2021). "Finally, FGF23 levels correlated with fibrosis in heart failure patients with preserved ejection fraction (HFpEF)." (PMID 34422725, 2021). "Moreover, multiple studies have indicated the crucial involvement of FGF-23 in heart failure pathophysiology." (PMID 35008591, 2021). "Another meta-analysis study of 34 studies which included 9 non-dialysis CKD populations found that a higher FGF-23 level increased the risk of myocardial infarction, heart failure and stroke." (PMID 34683112, 2021). "As a post hoc sensitivity analysis, we also adjusted NT-proBNP and FGF23 by both heart failure and renal function as these diseases may elevate both biomarkers." (PMID 33534825, 2021). "In patients with heart failure, FGF-23 levels are elevated and predict cardiovascular events." (PMID 34222283, 2021). "It is well known that the sympathetic activity is increased by MI or heart failure, which may be one of the reasons for elevation of the plasma FGF23 concentration in our mice with MI and heart failure." (PMID 33460402, 2021). "Furthermore, we aimed to assess the capability of FGF23 to predict the one-year mortality in comparison with the well-established Seattle Heart Failure (SHF) Model." (PMID 34330955, 2021). "We also stratified NT-proBNP by heart failure status and FGF23 by renal function." (PMID 33534825, 2021). "Elevated FGF23 is associated with all-cause and cardiovascular mortality and with heart failure in patients with or without CKD." (PMID 33534825, 2021). "This study aimed to assess plasma fibroblast growth factor 23 (FGF23) in patients with heart failure with preserved ejection fraction (HFpEF) and its relation to inflammation, renal function, clinical and imaging characteristics, exercise capacity, and prognosis." (PMID 32935918, 2020). "An independent relationship between increased circulating levels of FGF-23, incident heart failure and cardiovascular mortality has previously been described in large community-based studies and, recently, a similar relationship was confirmed in a larger cohort of patients with type 2 diabetes." (PMID 32998751, 2020). "Furthermore, in the Framingham Heart Study serum levels of FGF-23 correlated with total mortality, whereas, in LURIC trail, increased FGF-23 was associated with higher mortality in patients with heart failure and reduced ejection fraction." (PMID 31275638, 2019). "Previous studies have shown a higher occurrence of recurrent cardiovascular events in the highest quartile of FGF-23 in patients with acute coronary syndrome as well as worse outcomes in patients with known RD, including increased frequency of heart failure and mortality." (PMID 31659218, 2019). "From this we hypothesize that local overexpression of sKlotho may compensate for Klotho-independent maladaptive effects of FGF23 in an autocrine or paracrine manner in human heart failure." (PMID 29849175, 2018). "The impact of O-GlcNAc by way of FGF23 will open new avenues for research in lung diseases associated with chronic airway inflammation such as COPD, cystic fibrosis, and asthma as well as metabolic disorders including diabetes and heart failure." (PMID 30538676, 2018). "In one cohort study, an increased risk for decompensated heart failure in stage 2–4 CKD patients that is associated with FGF23 was independent of renal function." (PMID 30200452, 2018). "Furthermore, we noted that plasma concentration of FGF23 measured using ELISA kit was significantly higher in mice with heart failure induced by MI than in sham group." (PMID 27579618, 2016). "We also confirmed that sFKN stimulation upregulated FGF23 in osteoblasts, in agreement with a postulation that FKN is increased in heart failure and osteoblasts may be a source of circulating FGF23 in heart failure." (PMID 27579618, 2016).